NAPG (NSF attachment protein gamma)
Description:
Required for vesicular transport between the endoplasmic reticulum and the Golgi apparatus.
Synonyms: GAMMASNAP
Tractability: Antibody: UniProt places it where antibodies can reach, with medium confidence; the Human Protein Atlas places it where antibodies can reach. PROTAC: ubiquitination databases record sites on it; its protein half-life has been measured.
Gene: Protein-coding gene on chromosome 18 (10,525,905 to 10,552,766, forward strand). Ensembl gene ENSG00000134265.
Subcellular location: Membrane; Golgi apparatus
Subcellular location (Human Protein Atlas): Plasma membrane
Pathways (Reactome):
Vesicle-mediated transport: COPI-dependent Golgi-to-ER retrograde traffic; COPI-mediated anterograde transport; COPII-mediated vesicle transport; Intra-Golgi traffic; Retrograde transport at the Trans-Golgi-Network
Gene Ontology:
Molecular function: protein binding; soluble NSF attachment protein activity; syntaxin binding
Biological process: intra-Golgi vesicle-mediated transport; intracellular protein transport; membrane fusion; protein stabilization; protein-containing complex assembly
Cellular component: extracellular exosome; lysosomal membrane; mitochondrion; plasma membrane; Golgi apparatus; membrane; SNARE complex
Genetic constraint (gnomAD): Loss-of-function variants: 20 observed, 34.43 expected, observed/expected ratio (o/e) 0.58, 90% interval 0.41 to 0.84. The upper end of that interval is the gene's LOEUF score, 0.84, which puts it in group 3 of 6, group 1 being the genes least tolerant of losing a copy. Missense variants: 308 observed, 309.92 expected, observed/expected ratio (o/e) 0.99, 90% interval 0.9 to 1.09. Synonymous variants: 125 observed, 109.63 expected, observed/expected ratio (o/e) 1.14, 90% interval 0.99 to 1.32.
Homologues: Orthologues: chimpanzee NAPG (100% identical), macaque NAPG (99% identical), mouse Napg (98% identical), rat Napg (97% identical), guinea pig NAPG (96% identical), dog NAPG (96% identical), pig NAPG (96% identical), tropical clawed frog napg (85% identical), rabbit NAPG (76% identical), zebrafish napga (74% identical), zebrafish napgb (73% identical), Drosophila melanogaster gammaSnap1 (38% identical), and 3 more. Paralogues in human: NAPA (25% identical), NAPB (24% identical).
Diseases named in the same sentence as NAPG in open-access papers:
NAPG is named in the same sentence as 2 diseases in open-access papers, as found by Europe PMC text mining. Sharing a sentence is not in itself a finding about the gene and the disease.
NAPG shares sentences with these, for which no sentence is quoted: hereditary hemorrhagic telangiectasia (1 paper); tumor (1).